IMP3 (IMP U3 small nucleolar ribonucleoprotein 3)
Diseases named in the same sentence as IMP3 in open-access papers (continued):
Sharing a sentence is not in itself a finding about the gene and the disease.
cancer (66 papers, 2010 to 2025). A tumor composed of atypical neoplastic, often pleomorphic cells that invade other tissues. "Previous studies have shown that dysregulation of IMP3 is associated with the growth, migration, adhesion, and energy metabolism of cancer cells." (PMID 38271139, 2024). "We observed that IMP3 down-regulation shows a protective effect toward cancer progression and identified the underlying molecular mechanism based on the control of Bcl-2 and Bcl-xL transcripts, two key mediators of the intrinsic apoptotic pathway." (PMID 37024466, 2023). "IMP3 has been considered as a cancer-associated protein and its overexpression represents a prognostic marker in a variety of human types of malignancy." (PMID 32692399, 2020). "Insulin-like growth factor-2 messenger RNA-binding protein 3 (IGF2BP3 or IMP3) is an oncofetal protein that is expressed in various cancer types, and its expression is often associated with poor prognosis." (PMID 32293476, 2020). "The gene that encodes IMP3 is present on chromosome 7p15 and plays an important role in the migration and adhesion of cells in various malignant neoplasms." (PMID 32692399, 2020). "We focussed our efforts to IMP3 mediated migration as our previously published results in GBM clearly reflect the importance of this molecule in this hallmark of cancer." (PMID 28465487, 2017). "Recent studies have shown that IMP3 is associated with the occurrence and development of several carcinomas." (PMID 25789070, 2015). "Several RBPs that are up-regulated in cancer tissue can modulate the expression of genes implicated in cell survival, which prompted us to hypothesise that IMP3 could control programmed cell death also in CRC cells." (PMID 37024466, 2023). "IMP3 also plays an important role in carcinogenesis and progression of colon cancer and can serve as a prognostic biomarker to identify patients with a risk of developing metastasis or recurrence of cancer after the colectomy." (PMID 34035433, 2021). "Leveraging publicly available datasets from the GEO database, our bioinformatics exploration unveiled a marked overexpression of IMP3 in primary cancer tissues relative to benign cervical tissues." (PMID 41614778, 2025). "IMP3 has been implicated in the induction of EMT, a cellular program that endows cancer cells with increased migratory and invasive capabilities." (PMID 39328205, 2024). "IMP3 has been reported to bind to 3’-UTR of target mRNA and stabilize them, which is one of the mechanisms it is implicated in for cancer." (PMID 38271139, 2024). "According to studies reported in the literature, IMP3 plays a role in the development of GCTs and acts as an oncoprotein that triggers growth, invasion and metastasis in malignant tumours." (PMID 39001474, 2024). "Some RNPs such as RBM3, IMP3, and CUG-BP1 facilitate the formation of drug resistance 22 while heterogeneous nuclear ribonucleoprotein K has been associated with cancer procession and high risk of metastasis." (PMID 37324186, 2023). "Subsequently, the clinical prognostic significance of IMP3 in CRC was investigated using public cancer databases." (PMID 37024466, 2023). "For instance, IMP3 binds and positively regulates expression of cyclin D1, D3 and G1 mRNA in multiple cancer cell lines, thereby sustaining cell proliferation." (PMID 35892887, 2022). "Most previous studies have shown that high expression of IMP3 is positively correlated with the occurrence or progression of cancer." (PMID 35706003, 2022). "In the context of cancer, there are numerous examples of the critical role of IMP3 favoring chemoresistance, aggressiveness and metastasis." (PMID 34997006, 2022). "GO and KEGG pathway analysis showed that these targets were mainly enriched in cancer, RNA binding, and transcription, indicating an important role for IMP3 in cancer." (PMID 34154626, 2021).
cancer (continued). "IMP3-positive expression was observed in 47/79 (60.8%) malignant cases, including 43/62 (69.4%) PDACs, 5/17 other malignant tumors, and 0/11 benign tumors." (PMID 34446759, 2021). "IMP3 is useful for predicting disease progression and clinical outcomes in each type of malignant tumor and in the differential diagnosis of benign and malignant tumors." (PMID 34006250, 2021). "IMP3 has characteristics suitable for the development of such carcinoma vaccine because it is highly immunogenic, often expressed in carcinomas, particularly in malignant cells." (PMID 34035433, 2021). "A previous study showed that the IMP3 protein was a protein partner of RNAs or a protein that regulates glycolysis levels in cancer cells." (PMID 33308298, 2020). "A previous study revealed that IMP3 is highly expressed in various cancers and can regulate the expression of various genes at the posttranscriptional level." (PMID 33308298, 2020). "IMP3 is an oncofetal RBP, implicated in migration, invasion, angiogenesis, cancer stem-like cell maintenance and is also associated with malignant and recurrent tumors." (PMID 28465487, 2017). "As IMP3 is known to play a critical role in numerous cancers, the present study analyzed its function in NSCLC." (PMID 25789070, 2015). "IMP3 can also stabilize cluster of differentiation 44 mRNA and promote pseudopod structure formation in cancer cells, i.e., IMP3 acts like an oncogene." (PMID 25789070, 2015). "Binding of IMP3 to mRNA transcripts exerts post-transcriptional control that influences key cellular functions involved in cancer progression." (PMID 25886367, 2015). "Intriguingly, IMP3 expression is undetectable in most adult tissues, but high-level expression has been found in malignant tumors." (PMID 25688268, 2015). "IMP3 is considered as the overexpressed K homology protein in carcinoma and also the activator of IGF-II mRNA translation." (PMID 25789070, 2015). "Re-activation of IMP3 expression is observed in many human cancers, including the ovary, the endometrium, and the cervix, correlating with increased risk of metastases and decreased survival." (PMID 25014991, 2014). "IMP3 overexpression in STIC or PSC was defined as >10% of the stained cancer cells with strong intensity of the cytoplasmic staining." (PMID 25014991, 2014). "Studies have additionally found that IMP3 can exert a marked effect on cellular adhesion and invasion during normal development and during the development of cancers." (PMID 25295085, 2014). "The positive expression of IMP3 in STIC ranged from 15% to 100% cancer cells with an average of 45.5%." (PMID 25038792, 2014). "IMP3 is orthologous to Xenopus Vg1RBP/Vera and mouse K-homology protein overexpressed in cancer (KOC), which has been shown to be transcriptionally overexpressed in cancer." (PMID 23687996, 2013). "The overexpression of IMP3 has been identified in a number of malignant tumors, including renal carcinoma, malignant pancreatic lesions, endometrial carcinoma, uterine cervical cancer and testicular cancer." (PMID 24137402, 2013). "The present study demonstrated that IMP3 is able to promote the aggressiveness of cancer behavior, resulting in a poor prognosis for patients with CRA." (PMID 24137402, 2013). "In adult tissues IMP3 expression is low or undetectable, but in malignant tumors is strongly expressed." (PMID 23190601, 2012).
cancer (continued). "The human IMP3 gene is located at chromosome 7p15 with an identical sequence to that of KOC (KH domain containing protein overexpressed in cancer) and shows an overall sequence identitiy of 59% with other mRNA binding family members." (PMID 20591150, 2010). "The discovery of IMP3 is not completely novel, IMP3 has been previously reported to be aberrantly expressed in several cancer types and its high expression is associated with poor prognosis." (PMID 40179105, 2025). "Moreover, multivariable analysis showed a significant association between the IMP3 expression and the CSS, OS, RFS, cancer-specific mortality and disease recurrence after RNU." (PMID 39272712, 2024). "High levels of IMP3 expression have been observed in lymph node metastases compared to primary tumors, suggesting a potential role for IMP3 in facilitating the metastatic spread of cancer cells through the lymphatic system." (PMID 39328205, 2024). "IMP3, an oncogenic fetal protein linked to advanced and aggressive cancers, is expressed only in malignant tumors and is not found in benign tissues." (PMID 38818470, 2024). "PoTER derives from GCNIS; specifically, it is part of NSGCT, it is a malignant tumour that develops metastases like primary teratoma or other germ cell tumours in 22–37% of cases and is characterized by anomalies of chromosome 12p and by IMP3 expression." (PMID 39001474, 2024). "The RNA-binding protein IMP3 is known as a cancer-specific gene." (PMID 37627115, 2023). "To address whether IMP3 controls cancer cell survival, we analysed cell death pathways in in vitro and in vivo experiments after IMP3 downregulation by siRNA or an antisense oligonucleotide." (PMID 37024466, 2023). "On the contrary, IMP3 protein expression is strongly upregulated in some malignant tumors." (PMID 36937398, 2023). "We found that triptolide downregulated the RNA-binding protein IMP3, which is required for ribosomal RNA processing and may predict prognosis in many cancers." (PMID 35366242, 2022). "Moreover, IMP1/ZBP1 and IMP3 have almost identical developmental expression patterns, and both are reported to be potential oncogenic proteins involved in a range of cancers." (PMID 34685634, 2021). "In addition, it proposed novel insights about the attributes of IMP3 in cancer initiation and progression through evaluation of its IHC expression in normal, benign neoplastic, and frankly malignant sinonasal SCC." (PMID 33680717, 2021). "Insulin-like growth factor 2 messenger RNA–binding protein 3 (IMP3) is a carcinoembryonic protein that plays a role in the cellular proliferation, adhesion, and infiltration of tumors in malignant neoplasms; however, its pathological role remains unclear." (PMID 34006250, 2021). "So far, IMP3 has been investigated in various malignant tumors." (PMID 34035433, 2021). "Moreover, IMP2 is more abundant than IMP1 and IMP3 in most cancer types and promotes an undifferentiated character of HCC." (PMID 31555647, 2019). "IMP1 and IMP3 are so-called ‘oncofetal’ genes because their high expression in embryonic development is strongly downregulated before birth, but frequently reappears in cancers." (PMID 28753127, 2017). "This suggests that developing drugs that block the activity of IMP3 could help the immune system to fight back and destroy cancer cells." (PMID 26982091, 2016). "For cancer therapy, IMP3 might be an excellent drug target due to its restricted occurrence in healthy tissues and its widespread occurrence in different kinds of cancer and especially in cases of unfavorable prognosis." (PMID 26982091, 2016). "Furthermore, over-expression of IMP3 in vivo has been shown to induce acinar-ductal metaplasia and increase the formation of malignant tumours in a lung model of metastasis." (PMID 25886367, 2015). "IMP3 overexpression has been observed in a number of malignant tumors, including renal carcinomas, malignant pancreatic lesions, endometrial carcinomas, and uterine cervical and testicular cancer." (PMID 25789070, 2015).
cancer (continued). "Based on earlier reports of interactions between IMP3 and mRNAs that contribute to the migration of other cancer cell lines, we decided to assess the effect of knocking down IMP3 on the expression of receptors for ECM proteins and microtubule-associated motor proteins." (PMID 25886367, 2015). "By enhancing the expression of lymphangiogenic factors or directly affecting lymphatic endothelial cells, IMP3 could contribute to the expansion of lymphatic networks, providing additional routes for cancer cells to disseminate to regional lymph nodes and beyond." (PMID 39328205, 2024). "Since IMP3 has emerged as a critical regulator of multiple important targets and pathways involved in cell survival, we examined whether IMP3 could act as a key regulator of cancer cell survival." (PMID 37024466, 2023). "Moreover, upregulation of IMP3 is predictive of poorer patient survival and a higher probability of distal metastasis, suggesting that IMP3 is critical for the progression of human cancer." (PMID 34154626, 2021). "Thus, IMP3 is expected to be a novel molecular target for cancer therapy." (PMID 25789070, 2015). "Additionally, in K562 leukemia cells, the inhibition of IMP3 has been shown to result in apoptosis, indicating that it may be vital for cancer cell survival." (PMID 25295085, 2014). "Insulin-like growth factor II mRNA binding protein 3 (IMP3), an oncofetal protein and member of the insulin-like growth factor II mRNA binding protein family, has recently raised attention since it appears to play an important role in cell-migration and adhesion in various malignant neoplasms." (PMID 20591150, 2010). "Genes differing insignificantly from healthy tissue were IMP-3, CDH1, IQGAP1, NEDD9, TKS5, WAS and ARPC4, indicating minimal alterations in their expression levels in the analyzed cancer samples." (PMID 37623256, 2023). "Insulin-like growth factor mRNA-binding protein 3 (IMP3), also known as IGF2BP3, is highly expressed in various cancers and can regulate the expression of various genes at the posttranscriptional level." (PMID 36937398, 2023). "In initial experiments, IMP3 protein expression was evaluated in three different CRC cell lines (DLD-1, HCT-116 and HT-29) and in non-cancer colonic epithelial cell line HCEC-1ct by Western blotting." (PMID 37024466, 2023). "Vg1RBP/Vera, also known as K homology domain-containing protein overexpressed in cancer (KOC), and human IMP3 are also orthologs." (PMID 35706003, 2022). "The effect of IMP1 on cancer-derived cells is conserved, while the roles of IMP2 and IMP3 vary in a cell-dependent manner." (PMID 35706003, 2022). "Insulin-like growth factor 2 mRNA binding protein 3 (IGF2BP3/IMP3/KOC), initially identified as an RNA-binding protein, is highly expressed in embryonic tissues and a variety of cancers." (PMID 29212181, 2017). "IMP3, another homolog of IMP1, has been shown to prevent miRNA-directed High-Mobility Group AT-hook 2 (HMGA2) mRNA decay in cancer and development." (PMID 27655671, 2016). "Insulin-like growth factor II mRNA-binding protein 3 (IMP3), an RBP involved in multiple steps of mRNA metabolism, is gaining pivotal importance in controlling the development and growth of different types of human cancer." (PMID 37024466, 2023). "In CRC, IMP3 regulates MEKK1 to activate MEK1/ERK signaling, driving cancer progression." (PMID 35366242, 2022). "According to some studies IMP3 is not expressed in benign tissues, acts as an oncoprotein triggering growth, invasion and metastasis in malignant tumors." (PMID 32144540, 2020). "IMP3 was described as a potential marker of malignant tumors since it is not expressed by benign tumors and is seen only in few normal adult tissues and in specific cell types." (PMID 32144540, 2020).
cancer (continued). "Insulin-like growth factor-II mRNA-binding protein 3 (IMP3), an oncofetal protein and member of the IMP family, has become a focus of attention as it appears to play a significant role in cell migration and adhesion in various malignant neoplasms." (PMID 24137402, 2013). "Indeed, we have examined several peptides derived from a variety of cancer-testis antigens that have the oncogenic activity, including KIF20A, DEPDC1, MPHOSPH1, URLC10(LY6K),TTK, KOC1(IMP3), CDCA1, RNF43, and TOMM34." (PMID 24237633, 2013). "According to the present results, IMP3 was expressed in the carcinoma lesions, but was almost absent in the adjacent tissue counterparts." (PMID 24137402, 2013). "Therefore, we explored the possibility that IMP3 could bind Bcl-2 and Bcl-xL mRNAs, known to be highly expressed in CRC tissue and with crucial role in cancer progression and therapy resistance." (PMID 37024466, 2023). "Studies have shown that IMP3 expression is negative in healthy mature tissue and is positive in malignant neoplasms of the colon, kidney, bladder, pancreas, stomach, breast and lung, and is associated with an advanced clinical stage with distant metastases and shorter overall survival." (PMID 34035433, 2021). "IMP3 is strongly expressed in malignant tumors but rarely in normal adult tissues." (PMID 32692399, 2020). "Here, we deepened the study on nine of them (ASS1, EIF4G1, GALNT7, GLUT1, IGF2BP3 (IMP3), ITGA4, RAN, SOD1, and THBS2) to ascertain whether they are truly mesothelial cancer driver genes (CDGs) or genes overexpressed in an adaptive response to the tumoral progression (“passenger genes”)." (PMID 32659970, 2020). "Immunohistochemistry (IHC) was carried out to examine IMP3 protein expression in specimens from 183 cases of non-muscle-invasive urothelial carcinoma, 20 cases of muscle-invasive urothelial carcinoma and 20 benign tissues adjacent to cancer tissue." (PMID 31277094, 2019). "Therefore, we dichotomized IMP-3 staining data as positive (≥10% of cancer cells stained positive) or negative (<10% of cancer cells stained positive) for further survival analysis." (PMID 26796627, 2016). "In accordance with our results, an inhibition of IMP3 would - next to other potential benefits - lead to an elevated stress ligand expression and thereby enlighten recent approaches of NKG2D ligand-based cancer treatment, for instance, immunotherapy by Natural Killer cell infusion." (PMID 26982091, 2016). "The oncofetal protein, insulin-like growth factor II mRNA-binding protein 3 (IMP3), is a member of the IMP family that has recently become a focus of attention, as it appears to be significant in the migration and adhesion of cells in range of malignant neoplasms." (PMID 25789070, 2015). "In conclusion, the present study found that IMP3 plays a significant role in the progression of NSCLC, and that it may potentially be used as an independent biomarker for prognostic evaluation of the cancer." (PMID 25789070, 2015). "Interestingly, the tubal IMP3 signature rate was also significantly higher than those in 10 (16%) of the 62 cancer cases without STIC (p < 0.05)." (PMID 25038792, 2014). "However, 15 (31%) of 48 patients with STIC and 10 (16%) of 62 cancer patients without STIC showed IMP3 signatures, respectively." (PMID 25038792, 2014). "Treatment of HCT-116 cells with IMP3 siRNA increased the sensibility of CRC cells to 5-fluoruoracil and oxaliplatin, suggesting that IMP3 knockdown could potentially be deployed as an anti-cancer drug in the combinatorial approaches with chemotherapeutic drugs." (PMID 37024466, 2023).